WNT5A (Wnt family member 5A)
Diseases named in the same sentence as WNT5A in open-access papers (continued):
Sharing a sentence is not in itself a finding about the gene and the disease.
tumor (continued). "This loss of tumor-suppressive effect of Wnt5a was restored by expressing Daple-WT but not by expressing the Daple-FA mutant, indicating that a functionally intact GBA motif in Daple is essential for Wnt5a to exert its tumor suppressive effects." (PMID 26126266, 2015). "When we looked at non-tumor tissue, we did not detect reduced β-catenin signaling in Wnt5a expressing glands despite an observed decrease in hyper-branching and alterations in the molecular markers for specific progenitor and basal cells, activities known to be mediated by canonical Wnt signaling." (PMID 25401739, 2014). "Wnt5a, for example, is often viewed as a "non-canonical" Wnt capable of antagonizing the Wnt/β-catenin signaling and has a role in limiting B-cell proliferation and functions as a tumor suppressor in hematopoietic tissue." (PMID 26056595, 2014). "The higher level of methylation in tumors compared to tumor-adjacent gastric tissues that was observed in GoldenGate analysis was observed again for both HOXA5 (mean difference = 16.4%, P < 0.001 by paired t-test) and WNT5A (20.0%, P < 0.001) in this independent series." (PMID 24674026, 2014). "Thus, despite some earlier indications from in vitro studies, these data show that the Wnt-5a status of the primary tumor does not affect its sensitivity to TAM." (PMID 23990917, 2013). "It must be pointed out that an upregulation of Wnt5a mRNA in a specific cancer type does not alone indicate a tumor promoting function, since this might very well go hand in hand with a reduced Wnt5a protein level." (PMID 22039506, 2011). "We next tested the hypothesis that the absence of Wnt5a or TGF-β signalling would redirect the phenotype of MMTV-PyVmT tumours to a phenotype consistent with activated Wnt/β-catenin signalling." (PMID 19344510, 2009). "The expression of Wnt5a did not vary significantly between normal tissues and superficial tumours (P = 0.4), normal tissues and invasive tumours (P = 0.3) or superficial tumours and invasive tumours (P = 0.2)." (PMID 9461004, 1998). "However, several functional characteristics of cancer cells, such as uncontrolled growth, capacity to migrate and to invade other tissues, or to promote tumor development (tumorigenicity), were not affected in vitro or in vivo when WNT-5A expression was reduced using shRNA in MPNST cells." (PMID 34771683, 2021). "The high expression of Wnt5a in GC, the lack of tumor initiation after overexpression in mice, and the evidence that will be reviewed in this section, collectively suggest that the predominant function of Wnt5a in GC is the regulation of cell migration and invasion." (PMID 32195251, 2020). "Indeed, ectopic WNT5A expression does not promote tumor progression." (PMID 31261741, 2019). "However, recent findings also suggested that noncanonical Wnt signaling pathways, such as a Wnt5a-mediated noncanonical signaling, might also serve as oncogene or tumor suppressor in a cancer cell type-dependent manner." (PMID 27895670, 2016). "A screen of Wnt expression in various established tumor cell lines showed that, in general, canonical Wnts were up-regulated in cancer cell lines relative to normal human mammary epithelial cells while the expression of non-canonical Wnts, including WNT5A, WNT5B and WNT16, was down-regulated." (PMID 23484019, 2013). "However, it appears that peritumoral liver tissues express high levels of Wnt5a protein that could trigger noncanonical Wnt signaling in adjacent tumor cells." (PMID 19849855, 2009). "Recent studies have shown that Wnt5a, a non-canonical Wnt ligand, activates the IDO1 pathway, thereby reinforcing immune suppression while sustaining metabolic adaptations that support tumor survival and proliferation." (PMID 40917745, 2025). "In a recent clinical study in which the expression and clinical impact of the WNT5A, WNT7B, FZD7 and GPC1 proteins were investigated in tumour samples, LUSC patients with no or minimal increase in WNT5A protein levels had the longest survival." (PMID 40223089, 2025).
tumor (continued). "WNT5a, categorized as a non-canonical WNT ligand, triggers pathways such as CaMKII-ERK, resulting in the release of tumor-promoting substances like CCL2." (PMID 41041337, 2025). "Interestingly an increased level of nuclear β-catenin in ovarian cancer is correlated with a favorable patient prognosis, so the growth-suppressing function of WNT5a in this tumor type may not stem from the inhibition of CTNNB1 signaling, but from the regulation via non-canonical WNT signaling." (PMID 36612190, 2022). "Furthermore, blocking Wnt5a and EphA2 activity with the two agents in combination, not only reduced tumorigenicity and invasiveness, in vivo, addictively but also prevented the recurrence of the tumor upon suspension of their intracerebral infusion after 14 days." (PMID 35414102, 2022). "Wnt5a, as a noncanonical Wnt member, induces activation of YAP signaling, thereby contributing to malignant tumor progression." (PMID 33654199, 2021). "WNT5A is a key regulator of non-canonical WNT-signaling, however, it can play diverse roles in different types of cells, including tumor cells." (PMID 32659938, 2020). "WNT5A is one of the most studied noncanonical WNT ligands and is shown to be deregulated in different tumor types." (PMID 26316480, 2015). "Consistently, the transcription of WNT5A and CCND2, but not CCND1, was also elevated in PIAS1 knockdown xenograft tumor samples." (PMID 24586797, 2014). "Previously, we showed that the absence of Wnt5a, a non-canonical signaling Wnt, in MMTV-PyVmT tumors led to increased tumor growth, a change in tumor phenotype to a more basal subtype, and increased canonical Wnt/β-catenin signaling." (PMID 25401739, 2014). "ROR receptors may participate in Wnt signaling by serving as co-receptors for FZDs and enhancing specific Wnt-5a/ROR/FDZ non-canonical intracellular signaling, which is involved in tumor cell proliferation and invasion/metastasis, particularly in bones." (PMID 37237541, 2023). "Since promoter methylation of Wnt5a induces transcriptional silencing in CRC cells, our results suggest that MSI and/or CIMP-high tumours may experience preferential repression of non-canonical Wnt activity." (PMID 21587258, 2011). "In further support of the inhibitory role of Wnt5a, it has been indicated that this noncanonical ligand is suppressed by several secretive and regulator mediators such as microRNA 567-5p (miR-567-5p) in CRC, suggesting that these factors determine the function of Wnt5a tumor suppressor." (PMID 34603445, 2021). "Despite the tumor-promoting function of WNT5a/FZD2 pathway was found in previous study, WNT5A is frequently silenced by promoter CpG methylation in ESCC, indicating that WNT5A may not be a critical ligand binding to FZD2 in ESCC progression." (PMID 32766155, 2020). "In addition to its effects on non-canonical Wnt activity, Wnt5a is also known to inhibit β-catenin accumulation in CRC cells, suggesting that MSI and/or CIMP-high tumours may also experience preferential activation of canonical Wnt activity." (PMID 21587258, 2011).
cancer (391 papers, 1998 to 2026). A tumor composed of atypical neoplastic, often pleomorphic cells that invade other tissues. "WNT5A has a consistent association with various cancer types, yet its potential as a biomarker remained largely unverified." (PMID 40223089, 2025). "In breast cancer, WNT5A seems to reduce migration and invasion of cancer cells and its loss of expression has been associated with a worse clinical course." (PMID 40003864, 2025). "Together, these data confirm that in cancer cells, differential DNA methylation of WNT5A is associated with changes in WNT5A gene expression." (PMID 39164966, 2024). "Given that WNT5A expression has been associated with multiple cancer types and many stages of disease,18WNT5A was prioritised for follow‐up here." (PMID 39164966, 2024). "The analysis showed that the methylation level of the WNT5A gene was closely associated with CNV in LUSC (FDR <= 0.0001) cancer type." (PMID 39176352, 2024). "The Wnt5a+ cancer associated fibroblasts were significantly associated with TNM stage, and recurrence." (PMID 38872420, 2024). "WNT5A is also implicated in metastasis of multiple cancer types, such as gastric, lung, colorectal, and oral squamous carcinoma." (PMID 38240752, 2024). "In the targeted mRNA group, the most prevalent transcript associated with effects on cancer stemness is WNT5A that acts via the WNT/β-catenin signaling pathway." (PMID 37950151, 2023). "Here, the authors show Pancreatic ductal adenocarcinoma (PDAC) epithelial cells with high level of Lin28b secrete Wnt5a to upregulate Lin28b expression in cancer-associated fibroblasts, which in turn promote growth of PDAC cells via production of PCSK9." (PMID 37898598, 2023). "According to a recent study, the opposing roles of WNT5A in cancer can be attributed to the encoding of two different splice isoforms, WNT5A-long (L) and WNT5A-short (S)." (PMID 37664052, 2023). "In cancer, WNT5A has mainly been implicated as an oncogenic protein that is involved in the invasion and metastasis of many cancers." (PMID 35742983, 2022). "Wnt5a both directly and indirectly triggers cancer-associated signaling pathways based on the cancer type." (PMID 34603445, 2021). "Additional pre-clinical studies using cancer models to assess this relative risk are warranted before Wnt5a can be considered for clinical translation." (PMID 34900719, 2021). "Aberrant WNT5A signaling is associated with several human pathologies such as inflammation, fibrosis, and cancer." (PMID 33905374, 2021). "WNT3A and WNT5A were proteins have been implicated in several biological processes, including regulation of cell fate and cancer proliferation." (PMID 34093821, 2021). "For instance, cancer-associated myofibroblasts (CAMs, also known as cancer-associated fibroblasts, or CAFs) from GC consistently displayed increased expression of Wnt5a, compared to adjacent tissue myofibroblasts (ATMs)." (PMID 32195251, 2020). "Wnt5a signaling has been implicated in the progression of cancer by regulating multiple cellular processes, largely migration and invasion, epithelial-mesenchymal transition (EMT), and metastasis." (PMID 31510045, 2019). "Wnt5a signalling is associated with diverse pathogenic diseases, such as inflammatory diseases, metabolic disorders, and cancer." (PMID 31097962, 2019). "In this work, we focused on Wnt5a, an extracellular ligand that has been implicated in cancer progression." (PMID 31510045, 2019). "Wnt5a acts as a tumor suppressor in various cancers, and its downregulation is often associated with lower disease-free survival in primary breast cancers and also in hematopoietic, prostate, and colon cancers." (PMID 31921137, 2019). "Wnt5a signalling has been linked to several human pathologies, such as inflammation, cancer, and fibrosis." (PMID 31097962, 2019). "These include genes already implicated in cancer metastasis and cancer signaling, like Wnt5A CTGF, SULF2, integrin B2." (PMID 29581836, 2018).
cancer (continued). "Altered WNT5A (long isoform) expression has been linked to multiple cancers, including breast, gastric, colorectal, and lung cancers." (PMID 29415994, 2018). "Further, WNT5A activates the WNT/protein kinase C (PKC) signaling pathway that is highly expressed in many cancers and causes chemoresistance by partly activating WNT/β-catenin signaling." (PMID 29882812, 2018). "A recent study indicated that the opposing roles for Wnt5a in cancer are due to the encoding of two different splice isoforms." (PMID 28859077, 2017). "Dysregulation of WNT5A has been associated with progression of various malignancies, but differences in the function of WNT5A in different types of cancer most likely reflect the fact that the cellular context is crucial in determining the action of WNT5A." (PMID 28886116, 2017). "Inflammation is a hallmark of cancer that promotes cancer progression; however a paradoxical pathological role for Wnt5a signaling in inflammation has been described, through promoting the secretion of both pro-inflammatory and anti-inflammatory cytokines." (PMID 27571105, 2016). "Altered WNT5A expression is associated with various cancers, although in most studies the focus has been on only one of the known WNT5A isoforms." (PMID 26978652, 2016). "While these studies highlight a significant role for Wnt5a in modulating cancer associated inflammation, additional studies are warranted." (PMID 27571105, 2016). "This Wnt5a upregulation led to activation of the Wnt/Ca2+ pathway, activating CaMKII which caused a major reorganization of cytoskeleton in cancer cells by decreasing the length and frequency of filopodia-like actin structures and enhancing cell motility." (PMID 27571105, 2016). "Wnt5a, Wnt5b, and Fzd2 13 are crucial proteins reported to associate with cancer stemness and mobility." (PMID 27139420, 2016). "Based on these evidences, Wnt5A is an important signal protein associated with drug-resistance in cancer." (PMID 25401518, 2014). "Both Wnt5a overexpression and macrophage infiltration have been implicated in inflammation and cancer." (PMID 24993819, 2014). "Associations of Wnt5a expression with clinicopathological factors and cancer-specific survival were analyzed." (PMID 24156409, 2013). "That WNT5A is a cancer-associated gene implicated in the invasion and metastasis of several human cancers, including colorectal, breast and pancreas, heightens the need to more fully understand the function and dysfunction of the Wnt non-canonical pathway." (PMID 21092292, 2010). "Mechanistically, Wnt5a derived from cancer-associated fibroblasts promotes Hedgehog-mediated SOX2 expression in PCa cells, showing that palmitate and cholesterol induce SOX2 expression through cancer–stromal interactions involving Hedgehog signaling and non-canonical Wnt signaling." (PMID 40821114, 2025). "Consequently, Foxy-5 has shown potential in preventing metastasis to a certain extent by compensating for the deficient WNT5A activity, thereby inhibiting the proliferation of cancer cells." (PMID 39123414, 2024). "Additionally EMT in cancer cells has been linked to a number of signaling effectors including WNT5A." (PMID 36940196, 2023). "When receptor ROR2 binds to a small amount of WNT5A, it could slow down the secretion of cytokines and chemokines from cancer cells, regulating the mutated LRSAM1." (PMID 35164166, 2022). "WNT5A was linked with invasion of cancer cells, but this gene might be involved in invasion of pituitary prolactinoma cells." (PMID 33709028, 2021). "Furthermore, several reports have already suggested that Wnt5a plays an important role in cancer-associated inflammation." (PMID 34108990, 2021). "Wnt5a is a non-canonical Wnt ligand which is overexpressed specifically in BLBC cell lines, and the inhibition of the Twist-bromodomain containing 4 (BRD4) association by JQ1 reduced Wnt5a expression and suppressed invasion, cancer stem cell (CSC)-like property, and tumorigenicity of BLBC cells." (PMID 31462314, 2019).
cancer (continued). "Besides its crucial role in embryonic development, deregulation of Wnt5a has been implicated in several human diseases, most importantly cancer." (PMID 31510045, 2019). "Moreover, WNT5A and its receptors have been implicated in different human cancer entities including glioblastoma, leukemia, and pancreatic cancer." (PMID 29930766, 2018). "Moreover, aberrant WNT-5A signaling is associated with several human pathologies such as cancer, fibrosis, and inflammation." (PMID 26514730, 2016). "Several studies suggest that similar effects may be observed in Wnt5a-related cancer-associated inflammation." (PMID 27571105, 2016). "In the human digestive tract, there is a growing body of evidence that mutations or epigenetic changes of Wnt5a and Ror2 are associated with malformations and cancers, although their functions in regulating the adult stem cells remain almost unknown." (PMID 25211363, 2014). "Altered WNT5A expression has been associated with a number of cancers." (PMID 24260410, 2013). "The precise mechanisms governing cancer promotion caused by Wnt-5a downregulation are still unknown." (PMID 19603030, 2009). "Additionally, WNT5A is associated with prognosis in several other cancers." (PMID 39385172, 2024). "Nevertheless, more lines of evidence indicated that activation of Wnt5a-mediated signaling was associated with malignant capacity of many cancer types, which exhibited paradoxical effects on tumorigenicity, resistance to therapeutic agents, and/or metastasis in a cancer cell type-dependent manner." (PMID 27895670, 2016). "However, whether the mechanism that underlies Wnt5a regulation of cancer cell proliferation is similar to the mechanism by which it regulates cancer cell migration and invasion is unknown." (PMID 25622531, 2015). "Importantly, the expression of Wnt5a protein is controlled by the NF-κB signaling pathway, which may be implicated as an essential mediator not only for infection, but also for cancer development." (PMID 24278135, 2013). "Leptin promotes cancer cell progression and metastasis by tumor cell proliferation induction and cancer cell apoptosis inhibition via Wnt5a/JNK, STAT3/5 and MAPK/ERK1/2 pathways activation." (PMID 40227577, 2025). "-PDE6 plays an oncogenic role in several cancers by disrupting cyclic nucleotide signaling, Wnt5a-Frizzled-2 pathway, and ERK activation-PDE6H knockout suppresses mTORC1 signaling and mitochondrial function, and induces cell cycle arrest." (PMID 41179677, 2025). "By applying sophisticated fluorescence fluctuation techniques, FIDA and FCS, we quantitatively characterized transport vehicles in the extracellular fluid of WNT5a, a protein with diverse roles and implications in diseases such as cancer." (PMID 40165582, 2025). "WNT5A is a β-catenin-independent ligand with a dual role in cancer, both oncogenic and tumor-suppressive." (PMID 40003864, 2025). "Our data further demonstrates that Wnt5a drives a signaling pathway that engages multiple components identified as important in the migratory phenotypes of other cancers." (PMID 41301074, 2025). "Their dysregulation contributes to cancer, with alternative Wnt signaling pathways (Wnt5a/b and Wnt3a) activating YAP/TAZ independently of canonical β-catenin signaling." (PMID 39851951, 2025). "Our study highlights the significant upregulation and activation of the YAP/TAZ pathway in HR HER2-positive cancer cells and identifies Wnt5a as a key regulator of YAP stabilization." (PMID 40542295, 2025). "Cigarette smoke exposure amplifies WNT5A expression at both mRNA and protein levels in human tissues, favoring chronic inflammatory conditions and cancer development." (PMID 41440381, 2025). "The UALCAN database was used to validate the expression of WNT5A in 15 cancer samples, which showed significant differences acquired from the GEPIA and TIMER databases." (PMID 39176352, 2024).